NHERF1 (NHERF family PDZ scaffold protein 1)
Diseases named in the same sentence as NHERF1 in open-access papers (continued):
Sharing a sentence is not in itself a finding about the gene and the disease.
Chordoid Meningioma (2 papers, 2018 to 2020). A WHO grade II, usually recurring meningioma characterized by the predominance of tissues that are histologically similar to chordoma. "In this study, we also explored the use of NHERF1 as potential diagnostic marker for chordoid meningioma." (PMID 29983887, 2018). "We have previously shown that chordoid meningioma is characterized by ED with formation of microlumens reliably detected by NHERF1 IHC." (PMID 31963394, 2020). "This study uncovers features of epithelial differentiation in meningioma and proposes NHERF1 immunohistochemistry as a method of discriminating chordoid meningioma from neoplasms with similar appearance." (PMID 29983887, 2018). "In the part-chordoid category, two of the three grade I tumors had similar patterns as the NHERF1-diffuse positive chordoid meningiomas, and the third had focal pattern." (PMID 29983887, 2018). "We confirmed that secretory meningioma contains intracytoplasmic lumens/inclusions and microlumens, and additionally found that chordoid meningioma contains NHERF1-labeled microlumens that were further characterized ultrastructurally." (PMID 29983887, 2018). "To confirm that the NHERF1-positive dot-like structures represented microlumens, we performed an ultrastructural analysis of two representative NHERF1-diffuse positive chordoid meningioma cases." (PMID 29983887, 2018). "In a large cohort of 25 chordoid meningiomas, 72% and 12% of the tumors showed diffuse or focal NHERF1 microlumen labeling, respectively." (PMID 29983887, 2018). "Whether KLF4 and/or the progesterone receptor that appears to be highly expressed in secretory and chordoid meningioma (MM Georgescu, unpublished observations) play a role in NHERF1 upregulation remains to be investigated." (PMID 29983887, 2018). "NHERF1 also labels microlumens in chordoid meningioma, an epithelial variant not previously known to harbor these structures, and ultrastructural analysis confirmed the presence of microlumens in this variant." (PMID 29983887, 2018). "Consistent with the role of NHERF1 in epithelial differentiation with its loss shown to induce EMT, we found lower overall NHERF1 expression in a subset of chordoid meningiomas displaying fibroblastic appearance and the high-grade sarcomatous forms or areas completely lacked NHERF1 expression." (PMID 29983887, 2018). "In addition, we discovered that chordoid meningioma displays microlumens strongly labeled by NHERF1, consistent with the epithelial differentiation in this histologic variant." (PMID 29983887, 2018). "Their presence might explain the robust NHERF1 staining in chordoid meningioma." (PMID 29983887, 2018). "By using the clinically-validated NHERF1/EBP50 as marker for microlumens, chordoid meningiomas were divided into three ED tumor groups." (PMID 31963394, 2020).
ependymal tumor (2 papers, 2015 to 2021). A group of neoplasms which arise from the ependymal lining of the cerebral ventricles and from the remnants of the central canal of the spinal cord. "We show here that NHERF1 IHC has a high sensitivity and specificity for microlumen detection in ependymal tumors, and therefore can be used reliably as a diagnostic marker in these tumors." (PMID 25775275, 2015). "The immunohistochemical of ependymal tumors showed a unique expression of NHERF1 and some NHERF1-associated molecules, such as moesin, in microlumens that represent precursor polarized membrane structures retained by neoplastic ependymal cells." (PMID 25775275, 2015). "Strikingly, in ependymal tumors NHERF1 remained prominently retained in perinuclear dot-like structures that correspond ultrastructurally to microlumens, polarized structures characteristic for neoplastic cells of ependymal origin." (PMID 25775275, 2015). "In ependymal tumors, NHERF1 expression was retained in polarized membrane structures, such as microlumens, rosettes and canals, where it co-localized with some of its ligands, such as moesin and PTEN." (PMID 25775275, 2015). "The specificity of NHERF1 microlumen pattern as diganostic marker for ependymal tumors was assessed by screening 54 tumors of different origin that are typically considered in the differential diagnosis." (PMID 25775275, 2015). "Although these medications are being developed for other indications, the combination of NHERF1 PDZ1 inhibitors with β-catenin inhibitors may have a role in future care of ependymal tumors." (PMID 34944845, 2021). "Thus, in an analogous manner to other cancers, the regulation of morphogenesis and cell growth by NHERF1 subcellular localization emerges also in ependymal oncogenesis, with direct translation to the diagnosis of ependymal tumors." (PMID 25775275, 2015).
Hypertension (2 papers, 2022 to 2024). The presence of chronic increased pressure in the systemic arterial system. "While NHERF1 transfection restored dopamine signaling, this could represent a mechanism for the progression of hypertensive disease in NHERF1-deficient subjects." (PMID 38785509, 2024). "NHERF1 is a central player in the inflammatory response arising from chronic insults, such as aging and hypertension." (PMID 38785509, 2024). "Last but not least, the scaffolding protein NHERF1 could prove a potential future target for the reduction of renal fibrosis and inflammation, increasing the resistance to endogenous and exogenous nephrotoxins and even controlling hypertension." (PMID 38785509, 2024).
lung adenocarcinoma (2 papers, 2016 to 2020). A carcinoma that arises from the lung and is characterized by the presence of malignant glandular epithelial cells. "Using the ALK-positive and ALK-negative lung adenocarcinoma specimens collected from Beijing Xuanwu Hospital, we analysed the expression of NHERF1 by immunohistochemistry on tissue sections." (PMID 32164629, 2020). "Upregulation of NHERF1 in lung adenocarcinoma needs to be scrutinized during the administration of ALK-targeting drugs." (PMID 32164629, 2020). "Apical plasma membrane NHERF1 labeling was present in all cases, either diffuse, as in the serous carcinoma of the ovary case and a subset of papillary thyroid carcinoma and lung adenocarcinoma, or focal, in the remainder of the cases." (PMID 27229317, 2016). "Relative NHERF1 mRNA in lung adenocarcinoma was over the normal tissues (p < 0.01)." (PMID 32164629, 2020). "By characterization the effects of NHERF1 with its regulation on tumor cell responses to crizotinib, we have demonstrated a dynamic interplay between NHERF1 and ALK signaling in lung adenocarcinoma cells." (PMID 32164629, 2020). "We found that the NHERF1 staining was much more intensive in samples of ALK-translocated tissues, compared to that in ALK-negative lung adenocarcinoma tissues." (PMID 32164629, 2020). "The possible mechanisms of NHERF1 and its role in the cell sensitivity to crizotinib were investigated using an ALK-positive and crizotinib-sensitive lung adenocarcinoma cell line H3122." (PMID 32164629, 2020). "To address whether NHERF1 expression could be a consequence upon the activation of ALK signaling, we conducted laboratory experiment in H3122 cells, which is known as a commonly used ALK-positive and crizotinib-sensitive lung adenocarcinoma cell line." (PMID 32164629, 2020).
meningioma (2 papers, 2018 to 2020). A generally slow growing tumor attached to the dura mater. "In this study, we screened a large array of histologic variants of meningioma for microvillus formation using NHERF1, a marker that labels microvilli from diverse tissues." (PMID 29983887, 2018). "To explore epithelial differentiation in meningioma, we used NHERF1 antibody to immunolabel several variants of meningioma." (PMID 29983887, 2018). "To explore epithelial differentiation in meningioma, we labeled with NHERF1 antibody 83 cases of meningioma including the most common variants and all three WHO grades." (PMID 29983887, 2018). "To assess the diagnostic utility of NHERF1 in meningioma, specifically for the chordoid variant, we explored the NHERF1 labeling patterns in a panel of 12 tumors with similar morphological appearance, including cases of chordoma, chordoid glioma of the 3rd ventricle and chondrosarcoma." (PMID 29983887, 2018). "The three cases of clear cell meningioma had a mixed membranous and dot-like pattern of NHERF1 expression, with extensive membranous component." (PMID 29983887, 2018). "For the chordoid and part-chordoid meningiomas, we noted three patterns of NHERF1 expression: cytoplasmic, dot/microlumen-like and membranous." (PMID 29983887, 2018). "Of the 20 atypical meningioma cases, 4 (20%) were found to display either focal (n = 2) or more diffuse (n = 2) NHERF1 microlumen staining, as well as membranous expression, whereas the reminder (80%) were negative." (PMID 29983887, 2018). "The structures containing microvilli are most likely responsible for the NHERF1 labeling observed in secretory meningioma." (PMID 29983887, 2018). "Here, we explored epithelial differentiation in meningioma by using NHERF1 to detect polarity structures." (PMID 29983887, 2018). "Due to this key structural role, the expression of NHERF1 in conjunction with ERM proteins would be expected in tumors with epithelial differentiation, including the meningioma variants harboring this differentiation." (PMID 29983887, 2018). "We found that secretory meningioma contains intracytoplasmic inclusions/lumens and microlumens labeled by NHERF1, consistent with the established epithelial differentiation of this variant." (PMID 29983887, 2018). "NHERF1 did not detect microlumens in the most common variants of meningioma, including meningothelial, fibrous, transitional and psammomatous." (PMID 29983887, 2018). "Surprisingly, the NHERF1 labeling pattern was suggestive of the presence of microlumens in a subset of WHO grade II and grade III meningiomas demonstrating clear cell, rhabdoid, papillary, pseudopapillary or sheeting morphology." (PMID 29983887, 2018). "Indeed, the opposite NHERF1 IHC pattern, i.e. lack of membranous staining and high cytoplasmic expression, is noted in association with microlumens in most cases of chordoid or secretory meningioma." (PMID 29983887, 2018). "Although the role of KLF4 in the differentiation of meningioma is not known, it would be intriguing to explore if it controls the transcription of NHERF1, ERMs or other proteins involved in epithelial polarity." (PMID 29983887, 2018). "The NHERF1-negative tumors (n = 4) had only weak cytoplasmic expression similar to grade I meningiomas and mostly fibroblastic appearance." (PMID 29983887, 2018). "As the ED group #1 showed a distinct overall clinic-pathologic profile, with NSB location, absence of NHERF1 microlumens, and lack of overall recurrence, an interpretation of metaplastic meningioma, WHO grade I, appears to correspond more accurately to the biology of these tumors." (PMID 31963394, 2020).
Osteopenia (2 papers, 2018 to 2024). Osteopenia is a term to define bone density that is not normal but also not as low as osteoporosis. "Mineral-ion wasting and osteopenia in humans harboring NHERF1 mutations underscores the importance of this interaction." (PMID 38465463, 2024). "Moreover, the mice lacking NHERF1 and adult humans harboring NHERF1 mutations suffer from osteopenia, which might be due to abnormal osteoblast differentiation." (PMID 30463370, 2018).
pilocytic astrocytoma (2 papers, 2015 to 2016). Pilocytic astrocytoma is a rare subtype of low-grade glioma of the central nervous system characterized by a well circumscribed, often cystic, brain tumor with a discrete mural nodule and long, hair-like projections that extend from the neoplastic astrocytes. "Similarly, NHERF1 polarity structures were absent in glial tumors such as pilocytic astrocytoma, oligodendroglioma, mixed oligoastrocytoma and anaplastic astrocytoma." (PMID 25775275, 2015). "Testing for NHERF1 IHC of a large series of other CNS neoplasms that could arise in any location, including the pineal gland, did not detect microlumens in 22 cases of WHO grade II and III diffuse gliomas, 4 cases of pilocytic astrocytomas and 2 cases of atypical teratoid/rhabdoid tumors." (PMID 27229317, 2016).
rhabdoid tumor (2 papers, 2015 to 2016). An aggressive malignant embryonal neoplasm usually occurring during childhood. "For posterior fossa pediatric tumors, medulloblastomas consistently lacked NHERF1 polarity structures and the two cases of atypical teratoid/rhabdoid tumors screened were negative as well." (PMID 25775275, 2015).
schwannoma (2 papers, 2015 to 2022). A benign, usually encapsulated slow growing tumor composed of Schwann cells. "For adult posterior fossa and spinal cord tumors, schwannomas were negative for NHERF1 polarity structures." (PMID 25775275, 2015).
anaplastic ependymoma (1 paper, 2015). Anaplastic ependymoma is a rare, malignant type of ependymoma that most often arises in the supratentorial region of the brain of children and young adults and that manifests with variable symptoms including headaches, nausea, vision impairment, memory loss and difficulty walking. "Similarly, the loss of NHERF1 and associated proteins from the PM of ependymal polarity structures in anaplastic ependymoma is prone to result in PTEN cytoplasmic displacement and activation of the PI3K-Akt pathway." (PMID 25775275, 2015). "Besides this robust and specific NHERF1 expression that we propose as a diagnostic marker for these tumors, a gradual loss of NHERF1 was observed in anaplastic ependymomas, compatible with a previously demonstrated tumor suppressor role for NHERF1." (PMID 25775275, 2015).
atherosclerosis (1 paper, 2023). A disease characterized by the build-up of fatty material and calcium deposition in the arterial wall resulting in partial or complete occlusion of the arterial lumen. "SLC9A3R1 (also known as NHERF1 and EBP50 is a scaffolding protein of ezrin), also enriched in RA-pEVs, is known to be involved in the regulation of smooth muscle cell migration and in atherosclerosis, a disorder with pain and fatigue as comorbidity symptoms." (PMID 38274452, 2023).
cervical adenocarcinoma (1 paper, 2018). An adenocarcinoma arising from the cervical epithelium. "HeLa (cervical adenocarcinoma cell line with high level of NHERF1) and CaSki (cervical squamous cell carcinoma with low level of NHERF1) cells were chosen in this study." (PMID 29867145, 2018).
craniorachischisis (1 paper, 2016). Craniorachischisis is the most severe form of neural tube defect in which both the brain and spinal cord remain open to varying degrees. "However, the phenotypes associated with the disruption of Vangl2 (ablation, looptail mutations) are characterized by serious neural issues such as craniorachischisis and other severe neural tube defects, a phenotype not observed in NHERF1-/- or Celsr2/3-/- animals." (PMID 27055101, 2016).
cyst (1 paper, 2022). A sac-like closed membranous structure that may be empty or contain fluid or amorphous material. "In a different 3D cyst model grown from Caco-2 colorectal cells, NHERF1/EBP50 is similarly required for apical–basal polarization and lumen formation, but in conjunction with moesin rather than ezrin." (PMID 35198555, 2022).
gliosarcoma (1 paper, 2020). A rare histological variant of glioblastoma (WHO grade IV) characterized by a biphasic tissue pattern with alternating areas displaying glial and mesenchymal differentiation (WHO). "Expression of membrane-bound NHERF1 in these tumors but not in the initial gliosarcoma supports this hypothesis, as subcellular transitions of NHERF1 have been linked to the reversibility of these morphological changes." (PMID 32014051, 2020).
gynecological cancers (1 paper, 2022). "During recent years, its involvement in gynecological cancers has been explored, suggesting that NHERF1 could be a potential biomarker for the development of new targeted therapies suitable to the management of these tumors." (PMID 35223518, 2022).
lung carcinoma (1 paper, 2020). "From this study, a high level of NHERF1 expression was found in lung cancer tissues, especially in patients diagnosed with ALK-translocation." (PMID 32164629, 2020). "Previous studies showed that NHERF1 suppressed lung cancer cell migration by attenuating EMT process." (PMID 32164629, 2020). "NHERF1 expression in ALK positive lung cancer cells was regulated by ALK activities, and was in return able to alter the sensitivity to crizotinib." (PMID 32164629, 2020). "The expression level of NHERF1 in ALK-translocated NSCLC was significantly higher than that in other lung cancer tissues." (PMID 32164629, 2020). "The role of NHERF1 in drug resistance in lung cancers deserves more investigation for clues to understand the underlining mechanism." (PMID 32164629, 2020). "In lung cancers, NHERF1 protein was increased in both plasma and tissues from NSCLC patients." (PMID 32164629, 2020). "Ectopically overexpressed NHERF1 could be a functional protein for consideration to suppress lung cancers." (PMID 32164629, 2020). "We started to wonder if such pharmacologic functions of NHERF1 can also be observed in lung cancers, especially in ALK positive lung cancer cells." (PMID 32164629, 2020).
medullary breast carcinoma (1 paper, 2016). An infiltrating breast carcinoma with a relatively favorable prognosis. "A previously unknown sequence variant (TAC to TCC) was identified in the first exon of NHERF1 in a patient with medullary breast carcinoma, which would result in a switch of codon 24 (Tyr-Ser)." (PMID 27097111, 2016).
Meningothelial Meningioma (1 paper, 2018). A WHO grade I meningioma characterized by the presence of tumor cells that form lobules. "Interestingly, both NF2 and NHERF1 showed higher cytoplasmic expression in the secretory component of mixed secretory-meningothelial meningioma." (PMID 29983887, 2018).
metastatic tumors (1 paper, 2016). "We analyzed the expression of NHERF1 in 6 metastatic tumors with papillary architecture arising in various CNS locations, including posterior fossa." (PMID 27229317, 2016).
mucinous ovarian carcinomas (1 paper, 2022). An invasive malignant neoplasm that arises from the ovary and is characterized by the presence of malignant epithelial cells that contain intracytoplasmic mucin and may resemble the epithelial cells of the endocervix or gastrointestinal tract. "In detail, Tabrizi and colleagues demonstrated an unfavorable prognosis in mucinous ovarian carcinomas with NHERF1 expression." (PMID 35223518, 2022). "Ex vivo studies demonstrated an upregulation of NHERF1 in mucinous ovarian carcinomas and ovarian clear cell carcinoma (OCCC)." (PMID 35223518, 2022).